CRP (C-reactive protein)
Diseases named in the same sentence as CRP in open-access papers (continued):
Sharing a sentence is not in itself a finding about the gene and the disease.
Abdominal obesity (204 papers, 2006 to 2026). Excessive fat around the stomach and abdomen. "The accumulation of visceral fat observed in central obesity is associated with increased CRP levels mediated by the release of proinflammatory cytokines from the fat tissue." (PMID 41524907, 2026). "In the present study, we evaluated potential mediatory effects of inflammation, as reflected in elevated serum CRP levels, in the association between measures of general and abdominal obesity and CRC risk." (PMID 39791283, 2025). "This study confirms a strong association between hs-CRP and MetS, primarily influenced by central obesity." (PMID 40474309, 2025). "This study demonstrates a strong association between hs-CRP levels and MetS, with central obesity appearing to play a major mediating role in this relationship." (PMID 40474309, 2025). "The study found strong positive correlations between BMI (r = 0.76), WC (r = 0.81), and WHR (r = 0.78) with CRP levels, indicating that central obesity is closely linked to systemic inflammation." (PMID 39473678, 2024). "CRP was positively correlated with childhood obesity risk (OR = 2.301, 95%CI: 1.776, 2.982 for general obesity; OR = 2.165, 95%CI: 1.738, 2.697 for central obesity)." (PMID 39599620, 2024). "Our study suggests that central obesity plays a mediating role in the association of dietary quality with low-grade inflammation-related serum inflammatory markers (hs-CRP and WBC)." (PMID 36900791, 2023). "In the mediation effect analysis, both CRP and the TyG index significantly mediated the positive association between abdominal obesity (elevated WC) and CRC risk after adjustments were made for the confounding factors." (PMID 36407320, 2022). "Previous studies have shown a correlation of CRP with risk factors for MS such as abdominal obesity, hyperinsulinemia, IR, hypertriglyceridemia, and low HDL-cholesterol (Officers and Coordinators for the ALLHAT Collaborative Research Group, 2002)." (PMID 36685849, 2022). "The current study further explored how abdominal obesity modifies the association between sugar intake from SSBs and elevated CRP among non- and prediabetes US adults." (PMID 36613000, 2022). "A 1.69- and 2.66-fold increased risk of developing elevated CRP was observed in populations with prediabetes and abdominal obesity who consumed medium and heavy amounts of sugar intake from SSBs, respectively (all p ≤ 0.015)." (PMID 36613000, 2022). "CRP and the TyG index significantly mediated the positive association between abdominal obesity and CRC risk." (PMID 36407320, 2022). "Mediation effects of CRP and the TyG index were found for the association between abdominal obesity and CRC risk." (PMID 36407320, 2022). "Mendelian randomization showed increased waist-circumference, a marker of central obesity, associated with increased kynurenine, and increased kynurenine associated with C-reactive protein (CRP)." (PMID 34341450, 2021). "Higher maternal body mass index, familial hypertension as well as higher CRP z-score increased the risk for all four metabolic outcomes while low/medium parental education increased the risk of abdominal obesity and of showing several metabolic disturbances." (PMID 32943762, 2020). "Among women, central obesity and high levels of hs-CRP and SUA were independent risk factors for i-IGT." (PMID 33679598, 2020). "Among women, central obesity and high levels of hs-CRP and SUA were independent risk factors for i-IGT; low educational attainment and an elevated WBC count were independent risk factors for DM." (PMID 33679598, 2020). "In the subgroup analysis, men and women in their 20s with concurrent general and central obesity had the highest risk of elevated hs-CRP levels, and the risk decreased with increasing age." (PMID 33182500, 2020). "For instance, smoking, alcohol intake, and waist circumference were related to sex and age; hs-CRP was associated with MetS and sex, and abdominal obesity (WC) was also associated with body mass (BMI levels)." (PMID 33123092, 2020).
Abdominal obesity (continued). "Consuming instant noodles (women) and soda (men) were associated with elevated hs-CRP and soda consumption was associated with higher central obesity among men." (PMID 31469876, 2019). "Once beyond the specific cutoff for waist circumference to be defined as central obesity, multiple cardiovascular risk factors begin to appear, and therefore, CRP and IL-6 were rapidly reaching remarkably high circulating levels in individuals with MetS." (PMID 29670915, 2018). "Inadequate glycemic control, systolic blood pressure, increasing risk levels of hs-CRP, were in addition to abdominal obesity, also associated with triglycerides." (PMID 29785272, 2018). "Based on a previous study, high-sensitivity CRP (hs-CRP) is closely associated with abdominal obesity." (PMID 26177029, 2015). "Increased risk of elevated CRP was also seen among males with central obesity (although to a smaller extent than in females), and decreased risk was associated with higher alcohol intake, but statistical precision was limited for these estimates." (PMID 25163828, 2014). "In line with previous evidence in the general population, we found that central obesity independently is associated with CRP elevation at Type 2 DM debut, but primarily for females." (PMID 25163828, 2014). "It is possible that the association between CRP and age was due to the increase in abdominal obesity with age, and so was lost once waist circumference was accounted for." (PMID 21078191, 2010). "High concentrations of CRP in Indigenous participants were largely explained by other risk factors, in particular abdominal obesity." (PMID 21078191, 2010). "CRP is an independent risk factor for cardiovascular disease and abdominal obesity is associated with elevations of CRP." (PMID 16403234, 2006). "Furthermore, the adoption of multiple healthy lifestyle habits was inversely associated with CRP in adolescents with central obesity (p = 0.037)." (PMID 41682178, 2026). "Central obesity in children is independently associated with CRP, IL6 and TNF-α." (PMID 40195232, 2025). "Besides, studies have demonstrated that the relationship between lung function and abdominal obesity is also affected by CRP gene polymorphisms." (PMID 38926790, 2024). "The aim of this study was to investigate the correlation between the dietary patterns of children and both general and central obesity, as well as to explore the link between dietary patterns and CRP and the function of CRP in the association between dietary patterns and childhood obesity." (PMID 39599620, 2024). "Similarly, the significant relationships between BMI, Waist Circumference, WHR, and CRP levels observed in this study reinforce the idea that central obesity is closely linked to systemic inflammation." (PMID 39473678, 2024). "Furthermore, a lower SPISE index was significantly associated with T2D, abdominal obesity, and higher levels of adiponectin and C-reactive protein in adults and adolescents." (PMID 36677025, 2023). "Our findings demonstrated that abdominal obesity may magnify the association between high sugar intake from SSBs and elevated CRP, especially in individuals with prediabetes." (PMID 36613000, 2022). "In order to understand whether abdominal obesity modifies the association between sugar intake from SSBs and CRP levels, the stratified analyses were performed." (PMID 36613000, 2022). "This study aimed to explore whether PCF/TAT was associated with NAFLD/abdominal obesity (AO) phenotypes in different high-sensitivity C-reactive protein (hs-CRP) levels." (PMID 35121786, 2022). "Mediation effects of CRP and the TyG index were found for the association between abdominal obesity and CRC risk, which may help to elucidate the etiological importance of abdominal fat disposition rather than overall adiposity." (PMID 36407320, 2022).
Abdominal obesity (continued). "The increased ferritin concentration may be attributed to the increase in inflammatory status as a result of an increase in c-reactive protein concentration associated with central obesity." (PMID 33914792, 2021). "In model 3, log hs-CRP was significantly associated with abdominal obesity (β = 0.27, p < 0.001)." (PMID 34065158, 2021). "The strong associations we observed between metabolic disturbances and CRP z-scores are in line with other studies, which have shown that CRP levels in children and adolescents are positively associated with abdominal obesity, dyslipidemia and other MetS risk factors." (PMID 32943762, 2020). "Consuming instant noodles and soda were associated with elevated hs-CRP and central obesity." (PMID 31469876, 2019). "Cigarette smoking may cause abdominal obesity (an accumulation of visceral fat mass in the abdominal area), which may induce the production and secretion of CRP in the hepatocytes and endothelial cells." (PMID 25105149, 2014). "Among women, a lower risk of elevated CRP was observed in patients receiving statins (adjusted RR (aRR) 0.7 (95% confidence interval (CI) 0.6-0.9)), whereas a higher risk was seen in patients with central obesity (aRR 2.3 (95% CI 1.0-5.3))." (PMID 25163828, 2014). "In contrast with observations in the general population we found that in newly diagnosed type 2 DM patients, young age at DM debut was associated with substantially higher prevalence of CRP than older ages, after controlling for differences in central obesity and other factors." (PMID 25163828, 2014). "Furthermore, smoking changes the metabolism of nutrients and lipoprotein, β-cells function, and up-regulating inflammatory factors such as C-reactive protein, which can be associated with increased risk of cardio-metabolic disorders such as dyslipidaemia, central obesity and MetS." (PMID 36647030, 2023). "In addition, racial/ethnic differentials in C-reactive protein (CRP) levels, a known risk factor of abdominal obesity, could be at play." (PMID 37833560, 2023). "Furthermore, diets high in antioxidants could negatively be associated with plasma C-reactive protein (CRP), a major biomarker for systemic inflammation, and in turn, triggering metabolic disorders, such as central obesity and glucose intolerance." (PMID 36038871, 2022). "Patients with central obesity had significantly higher inflammatory markers (CRP), increased disease activity (DAPSA), and worse scores across all PROMs compared to those without." (PMID 41114009, 2025). "In women, central obesity correlated most strongly with CRP, whereas in men, percent body composition fat was a stronger predictor of systemic inflammation." (PMID 41158658, 2025). "The incidence of increased waist circumference, indicating abdominal obesity, and CRP ≥ 1 mg/L, were approximately 2.5 times higher than in subjects with lower calprotectin levels (<540.8 ng/mL)." (PMID 41440998, 2025). "Central obesity in women has the strongest correlation with CRP, while the fat percentage of systemic inflammation in men is a stronger predictor." (PMID 41158658, 2025). "A study conducted on the Swiss population found that obese individuals exhibited elevated levels of hypersensitive C-reactive protein (hs-CRP), whereas those with abdominal obesity showed increased levels of TNF-α." (PMID 40612555, 2025). "In abdominal obesity, visceral fat deposits become enlarged and dysfunctional and produce inflammatory biomarkers like C-reactive protein (CRP), cytokines, tumor necrosis factor-alpha (TNF-a), prostaglandins, and leptin." (PMID 40278381, 2025). "Lastly, abdominal obesity is often accompanied by chronic low-grade inflammation, characterized by elevated inflammatory markers like C-reactive protein and interleukin-6." (PMID 40092916, 2025). "Another inflammatory marker, C-reactive protein (CRP) is positively correlated with abdominal obesity in a clinical study." (PMID 39596205, 2024).
Abdominal obesity (continued). "A rare phenotype (node 8) with CRP ≤ 3 mg/L (mean: 1.4 (0.7; 2.7 mg/L)), presenting with central obesity (WHtR: 0.56 ± 0.04) and insulin resistance (FPI: 39.7 (29.2; 54.0 μIU/mL)) displayed the highest mean leukocyte counts." (PMID 38255379, 2024). "In other words, less active people were more likely to be obese; they had abdominal obesity and higher CRP levels." (PMID 39121088, 2024). "This study examined the link between dietary patterns of children and general and central obesity, including the role of C-reactive protein (CRP)." (PMID 39599620, 2024). "In a cohort of 740 patients, IL-6 and C-reactive protein (CRP) levels positively correlated with central obesity." (PMID 38247541, 2024). "In another, GH treatment in postmenopausal women with abdominal obesity reduced their serum markers of C-reactive protein and IL-6." (PMID 38405219, 2024). "The fruit and vegetable pattern showed an indirect negative effect on general and central obesity through the CRP pathway, demonstrating that CRP suppresses the relationship between the fruit and vegetable pattern and general and central obesity." (PMID 39599620, 2024). "Among the associations of HEI-2015 with hs-CRP and WBC, central obesity mediated 26.87% and 13.98%, respectively." (PMID 36900791, 2023). "In the association of DII with hs-CRP and WBC, central obesity mediated 15.24% and 10.83%, respectively." (PMID 36900791, 2023). "The increased risk of central obesity was associated with the increased level of hs-CRP and WBC (βhs-CRP = 0.661, 95%CI: 0.592, 0.730; βWBC = 0.582, 95%CI: 0.440, 0.724)." (PMID 36900791, 2023). "Central obesity, elevated SBP, and CRP were the most frequent features associated with both pre-MetS and MetS." (PMID 37371951, 2023). "Abdominal obesity is the main factor that increases CRP concentrations resulting from adiposity fat accumulation." (PMID 36319731, 2022). "In the present study, BMI and abdominal obesity were both strongly related to systemic inflammation (CRP) and CRP was strongly related to biological aging." (PMID 35586815, 2022). "We also observed a positive correlation between ZAG and CRP in non-central obesity group (R = 0.31, P < 0.01), as well in female group (R = 0.42, P < 0.01)." (PMID 35318405, 2022). "Hs-CRP concentration correlated also with waist circumference (r = 0.397, p < 0.001) and participants, who had central obesity (1.3 (IQR 2.2)) had higher hs-CRP compared to participants who did not (0.4 (1.0))." (PMID 35260816, 2022). "Several studies have shown that abdominal obesity may be associated with low-grade of systemic inflammation, which is characterized by an increase in pro-inflammatory cytokines, hematological inflammatory parameters and acute phase proteins such as C-reactive protein (CRP)." (PMID 35236423, 2022). "In this study, 73.6% of US adults with abdominal obesity had elevated CRP levels and were evaluated after adjustment for demographic factors, substance use, physical activity, and personal medical conditions." (PMID 36613000, 2022). "Abdominal obesity often has a pro-inflammatory state, characterized by elevated acute-phase reactants such as fibrinogen and CRP and a pro-thrombotic condition due to increased levels of PAI-1, clotting factors, and fibrinogen." (PMID 33996858, 2021). "As determined by the inclusion criteria, participants had abdominal obesity and slightly elevated plasma CRP levels (between 1 and 10 mg/l)." (PMID 32539794, 2020). "Study reported that black women were more likely to have CRP concentrations above 3 mg/L and that elevated CRP was more frequently observed in post-menopausal women, although it was strongly correlated with abdominal obesity." (PMID 32933066, 2020). "There was a significant difference between the two groups in terms of educational level, drinking and smoking status, physical activities, abdominal obesity (resp., p<0.001), and serum hs-CRP (p=0.008)." (PMID 31183378, 2019).
Abdominal obesity (continued). "The five components of MetS indicated that abdominal obesity and a high serum triglyceride (TG) concentration were tightly linked with ALT, SUA, LDL, and CRP; while a low HDL concentration and elevated blood pressure were related to enhanced ALT, UA, and CRP." (PMID 31752150, 2019). "Chronic stress and inflammation in adults have been associated with MUS, including pain and increased extracellular water, abdominal obesity, osteosarcopenia, a flattened salivary cortisol rhythm, and elevated circulating CRP concentrations." (PMID 30805908, 2019). "Abdominal obesity (AOR (CI) 5.3 (2.1–13.6)) and triglycerides (per mmol/l) (AOR (CI) 2.82 (1.68–4.93)) were associated with increasing risk levels of hs-CRP." (PMID 29785272, 2018). "Sub analyses (n = 171), showed that abdominal obesity (AOR 5.3) and triglycerides (per mmol/l) (AOR 2.8) were associated with increasing risk levels of hs-CRP." (PMID 29785272, 2018). "In conclusion, older women with a history of GDM who have developed IGT or T2DM have higher CRP and reduced adiponectin levels despite similar BMI and total and abdominal obesity to those with NGT." (PMID 29951553, 2018). "Even low levels of circulating CRP (2–6 mg/L), so called “high-sensitivity CRP” (hs-CRP), are indicative of an active inflammatory response to abdominal obesity in adults." (PMID 29273941, 2018). "In this study, a nearly statistically significant interaction between leptin and CRP was observed in men with abdominal obesity." (PMID 26632325, 2016). "High levels of inflammatory markers such as IL-6, tumor necrosis factor, and CRP are related to general and abdominal obesity." (PMID 25874126, 2015). "In a separate study, men with low-grade inflammation, high CRP levels and depressive symptoms were more likely to develop abdominal obesity during the 11-year follow-up." (PMID 24109426, 2013). "The results of the present study are in agreement with the findings of a correlation between central obesity and CRP." (PMID 21822486, 2012). "In our population with central obesity, measurement of hs-CRP cannot be used to further discriminate MetS status." (PMID 22417460, 2012). "Subjects with abdominal obesity (waist circumference ≥ 85 cm) showed higher serum hs-CRP and IL-6 levels and a lower adiponectin level than those without abdominal obesity." (PMID 17903275, 2007). "Given that central adiposity drives systemic inflammation, and WWI serves as a novel marker of central obesity, WWI may be associated with CRP levels." (PMID 42175467, 2026). "Additionally, central obesity correlates with increased inflammatory markers, such as C-reactive protein and interleukin-6, which contribute to atherosclerotic plaque instability and vascular remodeling." (PMID 40013043, 2025). "In the logistic regression analysis, ERFE was significantly associated with being overweight (OR = 0.051; p = 0.004), abdominal obesity (OR = 0.372; p < 0.001), HOMA-IR ≥ 2.0 (OR = 0.584; p = 0.013), CRP > 1 mg/L (OR = 0.648; p = 0.020) and triglycerides (OR = 0.521; p = 0.033)." (PMID 41156458, 2025). "However, a study comparing EPA (2.7 g) and DHA (2.7 g) in individuals with abdominal obesity and low-grade systemic inflammation found lowering of CRP, IL-6, IL-18, and TNF, where DHA was more potent than EPA." (PMID 40058591, 2025). "Furthermore, CRP showed a positive correlation with both general and central obesity (OR = 2.301, 95%CI: 1.776, 2.982 for general obesity; OR = 2.165, 95%CI: 1.738, 2.697 for central obesity)." (PMID 39599620, 2024). "Moreover, the association between central obesity and CKD was strengthened in the presence of elevated plasma C-reactive protein (CRP) levels, indicating that inflammation modifies the impact of central obesity on CKD risk." (PMID 39459455, 2024).